STAT3 (signal transducer and activator of transcription 3)
Diseases named in the same sentence as STAT3 in open-access papers (continued):
Sharing a sentence is not in itself a finding about the gene and the disease.
melanoma (continued). "Interestingly, analysis of microarray data generated from A375 melanoma cells treated with siRNAs against 45 transcription factors and signaling molecules (GSE31534) revealed that the silencing of STAT3 markedly reduced BCL2L10 mRNA levels." (PMID 33396645, 2020). "SiRNA against STAT3 has been delivered to melanoma cells through lipid conjugated PEI, via dissolving microneedles and gold nanoparticles, resulting in decreased STAT3 activity leading to the enhanced cancer cell apoptosis, decreased VEGF level and inhibition of tumor growth." (PMID 32059541, 2020). "Furthermore, the effects of BEA and BEA G1 were associated with the suppression of multiple molecular targets that play crucial roles in melanoma oncogenesis, including ERK, JNK, p38, NF-κB, STAT3, and MITF." (PMID 32340351, 2020). "In pilot studies, we have found that inhibitors of IKK (BMS-345541), JNK (SP600125) and TLR4 (TAK-242), but not inhibitors of ERK (U0126) and p38 (SB203580), block LPS-induced STAT3 activation, suggesting that IKK and JNK are involved in TLR4-signaling-mediated STAT3 activation in melanoma." (PMID 32312954, 2020). "Interestingly, the T-type calcium channel blocker mibefradil, which was previously shown to restore the sensitivity of resistant melanoma cells to BRAF and MEK inhibitors, was also able to reduce vem-induced HER3 and STAT3 activation." (PMID 33327495, 2020). "To determine whether TLR4 signaling involves STAT3 activation in melanoma cells, we used TLR4 ligands to stimulate the cells and examined STAT3 phosphorylation and nuclear localization." (PMID 32312954, 2020). "We further found that LPS promoted tumor growth and STAT3 activation in B16NC tumors, but had less effect in B16STAT3β tumors, indicating that STAT3 activation plays a positive role in TLR4 signaling-mediated melanoma growth." (PMID 32312954, 2020). "We therefore speculate that there is a TLR4/STAT3/PU.1 positive feedback loop in melanoma, which leads to the high expression of TLR4 and constitutive activation of STAT3." (PMID 32312954, 2020). "The TLR4/MYD88/STAT3 and TLR4/TRIF/STAT3 pathways established in this study shed novel insights into the pathophysiology of melanoma, and suggest new, potentially more effective, targets for treating melanoma." (PMID 32312954, 2020). "Notably, nicotine-induced α9-nAChR activity promoted melanoma cell proliferation through stimulation of the α9-nAChR-mediated AKT, ERK and STAT3 signaling pathways." (PMID 31835799, 2019). "High cell density has also been demonstrated to result in maintained STAT3 activity in melanoma, breast, bladder, and head and neck squamous cell carcinoma cell lines, although a link between STAT3 activity and IRF9 transcription has not been identified." (PMID 30679726, 2019). "In melanoma, ∆Ex2/3p73, but not ∆Np63α, mediates STAT3 (Tyr705) phosphorylation in an EPLIN/IGF-1R-dependent manner." (PMID 31569642, 2019). "Our results showed that STAT3 silencing by itself does not significantly affect neither proliferation nor cell death of WM9 melanoma cells likely because these cells harbor both BRAFV600E mutation and PTEN homozygous deletion." (PMID 30622697, 2019). "Additionally, it was suggested that quercetin inhibited the transcriptional activity of STAT3 and reduced the expression of STAT3 targeted genes such MM 2, MMP 9, Mcl-1, and VEGF in melanoma." (PMID 31064104, 2019). "STAT3 upregulates nodal factors of angiogenesis, mainly vascular endothelial growth factor (VEGF), hypoxia-inducible factor 1a (HIF-1α) and matrix metalloproteinase-2 (MMP-2) and fosters brain metastasis in melanoma." (PMID 31569642, 2019). "Importantly, suppression of STAT3 activity disrupts B-RAFV600E-mediated induction of anti-apoptotic proteins and reduces melanoma cell survival." (PMID 30691132, 2019). "Amoeboid melanoma cells secrete factors that are part of a network centered on NF-κB, while the second enriched network was centered on STAT3 (data not shown)." (PMID 30712866, 2019).
melanoma (continued). "Additionally, STAT3 regulates the MYC gene, which mediates escape of melanoma tumor cells from both terminal differentiation and G0/G1 arrest." (PMID 31569642, 2019). "The constitutive activation of STAT3 is a common denominator of several cancer types such as breast, lung, neck, and colon cancer and melanoma, and it is established by non-canonical pathways of STAT3 activation." (PMID 31500219, 2019). "The cellular uptake, anti-proliferation, and gene silencing efficiency of STAT3 siRNA PEI complex (PEI/siRNA) were observed with B16F10 melanoma cells in vitro, and the anti-melanoma activity of PEI/siRNA delivered by dissolving MNs was evaluated with mouse melanoma in vivo." (PMID 29348670, 2018). "Subsequently, OC downregulated STAT3 downstream signalling proteins, including myeloid cell leukaemia-1 (Mcl-1), B cell lymphoma-XL (Bcl-XL), MMP-2/9 and VEGF, which led to the apoptosis of melanoma cells." (PMID 29734791, 2018). "Further study exerted that ATL-I could suppress melanoma cell migration through the inhibition on p-JAK2, p-STAT3, MMP-2 and MMP-9." (PMID 30505341, 2018). "It has been further suggested that a balance between STAT1, STAT3, and STAT5 expression, upon interferon-mediated activation, impact the heterodimerization and transcriptional mechanisms driven by JAK-STAT activation in melanoma." (PMID 30166456, 2018). "Apart from STAT3, STAT1 has also been demonstrated to interfere melanoma development." (PMID 30166456, 2018). "Furthermore, we recently demonstrated that fad104 suppressed anchorage-independent growth of melanoma cells, and that the N-terminal region of FAD104 was essential for inhibiting malignant transformation and STAT3 activity." (PMID 29180690, 2017). "We additionally found other routes of GH induced signaling downstream of JAK2 and SRC, including GH-induced increases in phosphorylation states of STAT5, STAT1, STAT3 as well as of AKT, mTOR, and ERK1/2 in all four human melanoma cell lines." (PMID 28223541, 2017). "The most potent analogue, compound 1, inhibited the phosphorylation of JAK2 and STAT3 in human melanoma cells, but had no discernible effect on total JAK2 and STAT3 levels." (PMID 28570563, 2017). "Firstly, the levels of phosphorylated Stat3 (Tyr705) in four melanoma cell lines and one non-cancerous cell line (HEK293) were analyzed by western blot analysis." (PMID 26830149, 2016). "Furthermore, an inhibitor of STAT3 reduced downstream activity of TWIST1, which led to impeded migration and invasion of melanoma cells." (PMID 27876874, 2016). "When B16 melanoma or LLC cells were treated with conditioned medium from lal−/− MSCs, decreased proliferation of tumor cells was observed, accompanied by reduced activation of ERK1/2, p38MAPK, and STAT3 oncogenic molecules in tumor cells." (PMID 27531897, 2016). "Our findings suggest that SGI-1776 displays anti-melanoma effects in combination with BRAF inhibition in vivo; however, the inactivation of pathways such as PI3K and/or STAT3 may be necessary to obtain tumor regressions." (PMID 27448973, 2016). "Furthermore, our data revealed that IFNα clearly activates phosphorylation of STAT1 and STAT3 in THP1 and A375 melanoma cells." (PMID 26735690, 2016). "Since PIM kinases and AKT share common downstream effectors, we hypothesized that inhibiting both PIM and PI3K activity would prevent pathway compensation, enhance melanoma cell death compared to each single agent, and maintain low activity of AKT and STAT3." (PMID 27448973, 2016). "In contrast to the inhibition of STAT3 phosphorylation at tyr705site, IT treatment (20, 40 and 80 μM) for 24 h significantly increased AKT (ser473) and ERK (Thr202/Tyr204) phosphorylation in human melanoma A375S, A375R, A2058, and MEWO cells." (PMID 27323414, 2016).
melanoma (continued). "It was previously shown that ROCK stimulates STAT-3 activation through Janus Kinase 1 (JAK 1); STAT-3 and JAK 1 cooperate to control actomyosin contractility to mediate the rounded amoeboid migration in melanoma cells." (PMID 26418031, 2015). "PAX3 is activated by PI3 K (phosphatidylinositol 3-kinase) and STAT3 (signal transducer and activator of transcription 3) in melanoma cells, and a negative PAX3-dependent regulation of MITF expression is mediated by BRN2 encoded by POU3F2." (PMID 25433395, 2015). "Down-regulation of STAT3, by BRAF–MEK inhibitors may decrease the activity of anti-apoptotic protein Mcl-1 and reduce melanoma cell survival." (PMID 26322273, 2015). "In conclusion, STAT3 rs4796793 SNP is no predictive marker for the efficacy of adjuvant IFNα treatment in melanoma patients." (PMID 25593920, 2014). "Cells exposed in vitro to secretome of control melanoma cells or cells transfected with STAT3 siRNA before transplantation did not form tumors." (PMID 24344100, 2013). "Towards this aim, two melanoma cell lines (501mel and WM9) and melanoma cells freshly isolated from a patient were transfected with STAT3 siRNA, or scrambled siRNA, then exposed or not to the SSMC." (PMID 24344100, 2013). "B cells with or without Stat3 have opposite effects on tumor growth and tumor angiogenesis in both B16 melanoma and Lewis Lung Cancer mouse models." (PMID 23734190, 2013). "Further, a small molecule curcumin analog, FLLL32, induces apoptosis in melanoma cells via STAT3 inhibition without altering STAT1 signaling." (PMID 24199193, 2013). "G6PD may regulate apoptosis and expression of cell cycle-related proteins through phosphorylation of transcription factors STAT3 and STAT5, thus mediating formation and growth of human melanoma cells." (PMID 23693134, 2013). "Persistent expression and excessive activation of STAT3 and STAT5 is apparent in melanoma cells." (PMID 23693134, 2013). "STAT3 depletion did not affect basal survival of melanoma cells but STAT3 silencing using specific shRNA affected the survival of melanoma cells." (PMID 24170218, 2013). "Targeting the STAT3 pathway might help to circumvent the detrimental effects of the SSMC and to strengthen the efficiency of anti-melanoma therapies." (PMID 24344100, 2013). "Our study is the first to demonstrate the negative prognostic influence of p-STAT3 expression in stage IV melanoma patients that did not develop CNS metastasis but not in those patients that did develop CNS metastasis." (PMID 22488042, 2012). "Finally, SOID-8 suppressed melanoma tumor growth in a mouse xenograft model, accompanied with a decrease of phosphorylation of JAK2 and STAT3." (PMID 23166634, 2012). "Accordingly, SOID-8 inhibited IL-6-induced activation of STAT3 and JAK2 in melanoma cells." (PMID 23166634, 2012). "The SG600-IL-24 virus selectively lyses melanoma cells via an IL-20receptor-dependent mechanism which is independent of the STAT3 pathway." (PMID 22569271, 2012). "Intratumoral, nuclear p-STAT3 expression was not an independent univariate predictor of overall survival in stage IV melanoma patients (HR = 1.008; 95%CI: 0.998-1.015; n deaths = 222; p = 0.13)." (PMID 22488042, 2012). "The data presented here indicate that stage IV melanoma patients that do not have CNS metastasis should be stratified on the presence or absence of p-STAT3 expression during efficacy clinical trials." (PMID 22488042, 2012). "A similar specificity for STAT3 was also observed in the A375 human melanoma cell line, as IFN-γ-induced pSTAT1 was not altered and basal pSTAT3 was reduced after pre-treatment with FLLL32 or FLLL62." (PMID 22899991, 2012). "In cancers, STAT3 becomes activated constitutively through aberrant activation of tyrosine kinases, such as c-Src or Janus kinase (JAK) family members, thereby driving the malignant phenotype of cancer cells, including melanoma." (PMID 23166634, 2012).
melanoma (continued). "STAT3 has been shown to be a key transcriptional regulator of FoxP3 in Tregs, and Treg infiltration has been shown in melanoma patients to be a negative prognosticator and a predictor of local recurrence." (PMID 22488042, 2012). "Among the systemic melanoma metastasis of stage IV melanoma patients without CNS metastasis (n=151), p-STAT3 expression was 14.7% (SD = 14.6); whereas it was 13.3% (SD = 16.5) in the systemic melanoma metastasis of those patients with CNS metastasis (n=148)." (PMID 22488042, 2012). "STAT3 phosphorylation, STAT3 DNA-binding activity and total STAT3 levels have been shown to increase in A375 melanoma cells in a density-dependent manner in the absence of ligand." (PMID 22046235, 2011). "As a confirmation, in murine B16 melanoma and MB49 bladder carcinoma, IL-17 mediated tumor-promoting role involves a direct effect on tumor cells through IL-6 induction and subsequent signal transducer and activator of transcription 3 (STAT3) activation." (PMID 22171994, 2011). "FLLL32 inhibited STAT3 phosphorylation at Tyr705 but not at Tyr727 in multiple human melanoma cell lines after a 24 hour treatment." (PMID 20576164, 2010). "Apart from these fledgling molecular targets, a ubiquitous signal transduction pathway regulator, the signal transducer and activator of transcription 3 (STAT3) protein, has recently been shown in our laboratory to also play a critical role in melanoma induced brain metastases." (PMID 24281074, 2010). "Given that Ruxolitinib has been reported to modulate melanoma cell-intrinsic resistance to anti-PD-1, we wondered whether Ruxolitinib could mimic the function of SLC9A2 by inhibiting the STAT3 signaling pathway, thereby reversing immunotherapy resistance in CRC." (PMID 40474298, 2025). "14,15-EET induces G-CSF/IL-6 production in vivo, enhancing STAT3 activation in neutrophils to promote MMP-9 expression and suppress TRAIL expression, with neutrophil-derived MMP-9 being essential for inducing angiogenesis in dormant micrometastases in melanoma." (PMID 40564191, 2025). "Furthermore, it was discovered that by concurrently blocking the MAPK/c-Myc/cyclin D1 and STAT3/SOX2 pathways, a combination of DHT and MAPK pathway inhibitors could accelerate the death of melanoma cells." (PMID 39944829, 2025). "One of the challenges in treating melanoma patients with mitogen-activated protein kinase inhibitors (MAPKis), which target MAPK signaling pathways, is the development of drug resistance due to the activation of the signal transducer and activator of the transcription 3 (STAT3) signaling pathway." (PMID 40001571, 2025). "For the treatment of melanoma, hydroartemisinin could significantly reduce the levels of p-STAT3, p65, and IL-10 induced the p-STAT1 both in vitro and in vivo, indicating that dihydroartemisinin exhibits anticancer effects on melanoma by affecting STAT1/STAT3 pathway." (PMID 39202965, 2024). "It is not clear whether inhibiting STAT3 signal increases the sensitivity of melanoma cells to targeted drugs." (PMID 38822350, 2024). "In addition, unphosphorylated or phosphorylated STAT1 and STAT3 are coordinately upregulated by both IFN-α and IFN-γ and may represent a marker for the dynamic mechanism of melanoma progression and host response." (PMID 37047709, 2023). "Notably, coexpression of wild-type STAT3 but not the STAT3 phosphorylation mutants, attenuated the shSTAT3-induced sensitization of melanoma cells to sunitinib." (PMID 36720918, 2023). "To elucidate whether HLA-G stimulates STAT3 signaling in BMICs via SPAG9, we generated pooled SPAG9 knockout in HLA-G OE lung BMICs and probed for the expression of p-STAT3 (Y705) in control and SPAG9 knockout lung and melanoma BMICs." (PMID 36780531, 2023). "Interestingly, STAT3 is one of the transcription factors responsible for the increase in SERPINA3 gene expression after the stimulation of the integrin–FAK–AKT signaling pathway, which leads to the migration of melanoma cells." (PMID 36672665, 2023).
melanoma (continued). "Our findings revealed that EEF2K/p‐STAT3/SPP1 might be a novel oncogenic pathway in melanoma progression and could serve as an important reference point for potential combination therapy for melanoma." (PMID 35184394, 2022). "Furthermore, we found that p‐STAT3 could bind to the promoter region of SPP1 and enhance transcription, thus facilitating melanoma progression." (PMID 35184394, 2022). "From our RNA-Seq data we found that responding melanomas were mostly expressing IFN-γ, STAT3, cell apoptosis and DNA damage repair signalling pathway genes, whereas non-responding melanomas significantly expressed metastatic pathway genes, representing important differences in cell signalling." (PMID 36248850, 2022). "Moreover, it has been previously reported in melanoma cells that MEK-inhibitor resistance could also depend on the cross talk between ERK1/2 and Src/Fak/STAT3 signaling pathways, although this topic is still debated and context dependent." (PMID 35163058, 2022). "In this regard, a negative correlation has been previously found between ERK1/2 activation and the p-Tyr705-STAT3 expression level in pancreatic cancer cells; in addition, ERK or PI3K, the upstream kinase of Akt, can inhibit STAT3 tyrosine phosphorylation in human melanoma cells." (PMID 35163058, 2022). "We also observed a negative correlation of pSTAT3 with CD8 in both the GBM and melanoma (nivo) tumors, consistent with literature reports that STAT3 signaling may mediate immunosuppression." (PMID 34188042, 2021). "Interestingly, EGFR/STAT signaling may differ in human melanoma versus Xiphophorus Xmrk models since inhibition of c-Src kinase activity, but not EGFR, in human melanoma-derived cell lines, downregulates STAT3 signaling and Bcl-xL expression." (PMID 34067095, 2021). "In agreement with our earlier observation, we found that the expression of CDK2/4/6 shows a negative correlation with cytotoxic lymphocyte infiltration (CTL) in both GBM and melanoma, while STAT3 shows a negative correlation with CTL infiltrations in GBM but a positive correlation in melanoma." (PMID 33668805, 2021). "In our study, BEA and BEA G1 concurrently inhibited the activation of ERK1/2, JNK, p38 MAPK, NF-κB p65, STAT3, and MITF in A375SM melanoma cells, suggesting that the natural compounds may effectively inhibit aggressive melanoma by targeting multiple oncogenic molecular pathways." (PMID 32340351, 2020). "However, one study has shown that Ser727 phosphorylation is involved in cell survival and nuclear translocation of STAT3 regardless of Tyr705 phosphorylation in melanoma cells." (PMID 32422890, 2020). "Indeed, vemurafenib treatment of melanoma cells led to a reduction in c-Myc and Elk1 expression and Elk1 phosphorylation, while Stat3 expression and phosphorylation were not affected." (PMID 32719412, 2020). "In addition to regulating the transcription of cell cycle and apoptosis related target genes, Stat3 activation in melanoma cells controls matrix metalloproteinase-2 (MMP-2) expression through interacting with MMP-2 promoter, thus promoting melanoma invasion and metastasis." (PMID 32565740, 2020). "Moreover, apigenin impaired the migratory and invasive abilities and exerted antimetastatic effects on melanoma A375, G361 and B16F10 cells via inhibition of STAT3 nuclear organization and transcriptional activity as well as its target genes involved in cell migration and invasion." (PMID 32521759, 2020). "However, whether shikonin inhibits melanoma EMT and metastasis through STAT3/Twist inhibition needs to be further investigated." (PMID 32536866, 2020). "Previously, we showed that Stat3 deletion in moDCs used as a tumor vaccine enhances accumulation of effector CD8+ and CD4+ T cells, and suppresses FoxP3+ CD4+ T cell (Treg) accrual in melanoma tumors, correlating with decreased tumor growth and increased mouse survival." (PMID 31947933, 2020).